ATP7B (ATPase copper transporting beta)
Diseases named in the same sentence as ATP7B in open-access papers (continued):
Sharing a sentence is not in itself a finding about the gene and the disease.
Wilson disease (continued). "Copper excess can lead to various diseases, most prominently Wilson’s disease (WD), a rare autosomal recessive inherited metabolic disorder characterized by the pathological accumulation of Cu+ due to mutations in the ATP7B gene, resulting in hepatic, neurologic, and/or psychiatric symptoms." (PMID 39063122, 2024). "Genetic analysis revealed two ATP7B mutations, confirming the primary diagnosis of Wilson disease." (PMID 38306527, 2024). "Wilson’s disease (WD) is inherited in an autosomal recessive manner and is caused by pathogenic variants of the ATP7B gene, which are responsible for impaired copper transport in the cell, inhibition of copper binding to apoceruloplasmin, and biliary excretion." (PMID 39062788, 2024). "While the ATP7B K832R variant (rs1061472) is generally considered benign in Wilson’s disease, the ATP7B K832R (rs1061472) polymorphism has been shown to alter ATP7B properties in vitro and in vivo, affecting its trafficking and transporting activities as well as its serum Cu levels in humans." (PMID 38424191, 2024). "Wilson’s disease (WD) is a rare autosomal recessive disorder due to mutations in the ATP7B gene." (PMID 38255382, 2024). "Different ATP7B gene variants on chromosome 13q14.3 of patients with Wilson disease." (PMID 39559689, 2024). "Wilson’s disease (WD) (OMIM 277900) or hepatolenticular degeneration is an autosomal recessive hereditary disorder of copper metabolism that results from various pathogenic variants in the ATP7B gene." (PMID 39767741, 2024). "ATP7B (OMIM: 606882) is associated with autosomal recessive disorder Wilson disease (OMIM: 277900)." (PMID 39767564, 2024). "Wilson’s disease (WD) is an inherited condition resulting from impaired excretion of copper into the biliary tract by hepatocytes harboring mutations in transmembrane transporter protein, ATPase copper transporting beta." (PMID 37521690, 2023). "Mutations of ATP7A and ATP7B genes cause Menkes’ and Wilson’s diseases, respectively." (PMID 38136617, 2023). "Wilson's disease is an autosomal recessive disorder caused by ATP7B pathogenic mutations." (PMID 37681011, 2023). "Wilson’s disease (WD) is a copper metabolism disorder due to mutations of the ATP7B gene encoding for a hepatocyte copper carrier that induces an inability of the liver cell to evacuate copper as well as a significant decrease in the synthesis of circulating ceruloplasmin." (PMID 37563694, 2023). "Wilson disease (WD) is an inherited disorder of copper metabolism, which is caused by homozygous or compound heterozygous mutations (the presence of two different mutant alleles) in ATP7B." (PMID 36923697, 2023). "Mutations in ATP7B are associated with Wilson’s disease, a severe hepatic neurological disease." (PMID 37091865, 2023). "Wilson’s disease (WD) is an inherited disease characterized by copper metabolism disorder caused by mutations in the adenosine triphosphatase copper transporting β gene (ATP7B)." (PMID 37717021, 2023). "Pathogenic variants in ATP7A and ATP7B manifest as Menkes and Wilson disease, respectively." (PMID 36301669, 2023). "To date, hundreds of Wilson’s Disease-related mutations have been identified in ATP7B." (PMID 37091865, 2023). "Hepatic copper accumulation takes place in Wilson’s disease caused by mutations of ATP7B." (PMID 37311819, 2023). "Functional inactivation of ATP7B results in excessive deposition of copper in the liver and other tissues, which causes oxidative stress due to copper’s redox reactivity, and accounts for Wilson’s disease-associated hepatotoxicity." (PMID 37759956, 2023). "In addition, an analysis was performed regarding the Wilson disease that is associated with ATP7B homozygous mutation showing a prevalence of 38.7 per million people in Korea." (PMID 37728764, 2023).
Wilson disease (continued). "Wilson’s disease is an autosomal recessive disorder characterized by a profound accumulation of Cu, primarily in the liver, brain, and kidneys, due to mutations in the ATP7B gene that impair the ability to excrete Cu into the bile." (PMID 38139406, 2023). "Mutations in the ATP7B gene lead to failure of copper transport from hepatocytes into bile, resulting in Wilson disease, a copper toxicity disorder characterized by a dramatic build-up of intracellular hepatic copper with subsequent hepatic and neurological abnormalities." (PMID 35296237, 2022). "Wilson's disease (WD), also known as hepatolenticular degeneration, is an autosomal recessive disorder of copper metabolism and is caused by homozygous or compound heterozygous mutations in ATP7B." (PMID 35775054, 2022). "Moreover, due to the central role of ATP7B in Cu homeostasis regulation in the brain, neurological disorders are associated with Wilson disease." (PMID 36359796, 2022). "In addition to supporting evidence in human for the association between ATP7B and Wilson disease, RGD provides data for several animal models of Wilson disease." (PMID 34741192, 2022). "Wilson’s disease (WD) is a copper metabolic disorder caused by a defective ATP7B function." (PMID 35388883, 2022). "LmATP7 is also comprised of a hydrolase region containing TGDN and GXGXND conserved motifs in the ATP-binding site of the nucleotide-binding domain and the SXHP motif whose mutation in human ortholog ATP7B (His1069Gln) is the most frequent contributor to Wilson's disease in the Caucasian population." (PMID 34958799, 2022). "With regard to disturbances in the copper metabolism, Wilson disease (WD) is known as an autosomal recessive disease affecting primarily the Cu excretion via bile and the hepatic synthesis of ceruloplasmin caused by mutation in the ATP7B gene." (PMID 36421727, 2022). "Mutations in the ATP7B gene, which encodes the Cu-transporting P-type ATPase ATP7B, are associated with Wilson’s disease, a life-threatening disorder in which patients present with progressive Cu accumulation in several tissues, particularly the liver, brain, and cornea." (PMID 36414625, 2022). "In addition to annotations to Wilson disease and related Mammalian Phenotype annotations, the rat gene page provides links to the mutant allele and mutant strains with aberrant Atp7b genes." (PMID 34741192, 2022). "Wilson's Disease is a systemic disease, also known as autosomal recessive copper metabolism disorder caused by ATP7B gene mutation, leading to extra copper ions deposited in the liver, cerebrum, kidney, cornea, and other tissues because of hepatic copper excretion defect." (PMID 35865642, 2022). "In Wilson disease patients carrying ATP7B mutations with incomplete inactivation of the gene product, the polymorphisms may confer a clinically relevant modification of the phenotype or disease penetrance." (PMID 33828154, 2021). "Wilson Disease (WD) is a hereditary disorder predominantly attributed to hepatocellular Cu disposition due to Wilson ATPase dysfunction, a P1B-ATPase encoded by the gene ATP7B." (PMID 33668829, 2021). "In this report we used micro synchrotron X-ray fluorescence (μSRXRF) to image and analyse elements in gallbladder from patients with genetically documented Wilson’s disease in which Cu overload in liver cells are characteristic for their impaired hepatic copper transport due to mutation in ATP7B." (PMID 34940728, 2021). "The polymorphisms cannot be causative for Wilson disease, but they may still confer changes in ATP7B gene expression." (PMID 33828154, 2021). "Another autosomal recessive disease, the Wilson disease (also known as hepatolenticular degeneration), affects primarily the liver and basal ganglia of the brain, and is caused by mutations in the ATP7B gene and generation of defective Cu transport protein leading to Cu build up." (PMID 34732319, 2021).
Wilson disease (continued). "Furthermore, an autosomal recessive disorder, Wilson disease (WD), caused by defects of the ATP7B gene with excessive copper deposition in the body and patients’ brain examinations have shown copper concentration eight times greater than the controls." (PMID 33081348, 2020). "Moreover, prime editing functionally recovers disease-causing mutations in intestinal organoids from patients with DGAT1-deficiency and liver organoids from a patient with Wilson disease (ATP7B)." (PMID 33097693, 2020). "Mutations in the ATP7A and ATP7B protein genes lead to the disruption of normal Cu(I) distribution, causing serious neurological disorders in humans; these are known as Menkes disease and Wilson’s disease, respectively." (PMID 32748830, 2020). "Wilson’s disease (WD) is a rare autosomal recessive metabolic disorder resulting from mutations in the copper-transporting, P-type ATPase gene ATP7B gene, but influences of epigenetics, environment, age, and sex-related factors on the WD phenotype complicate diagnosis and clinical manifestations." (PMID 32485807, 2020). "Mutation in the ATP7B gene results in disturbances in copper binding to ceruloplasmin (CP) by the ATP7B protein and leads to copper accumulation in the liver up to the toxic level in patients with Wilson disease." (PMID 33260507, 2020). "A genetic deficiency of ASMase prevented Cu2+-induced hepatocyte apoptosis, while ASMase inhibition with desipramine in rats with a mutation in the Atp7b gene, a genetic model of Wilson’s disease, protects against Cu2+ -induced hepatocyte death and liver failure." (PMID 33143193, 2020). "Mutations detected in the ATP7B gene in Wilson disease patients during present study." (PMID 31059521, 2019). "The causative mutations for Wilson Disease are in the ATP7B gene." (PMID 31557851, 2019). "ATP7B gene mutations lead to ATP7B protein dysfunction, which in turn causes Wilson’s disease." (PMID 29649982, 2018). "Mutations in the ATP7B gene are the major cause of Wilson disease." (PMID 29540233, 2018). "Mutations in ATP7B are responsible for the autosomal recessive Wilson disease." (PMID 28459846, 2017). "For ATP7B, 15 (three silent, 12 Wilson disease-causing) variants in MBD3 are described." (PMID 26747866, 2016). "Another P‐type ATPase, ATP7B, is mutated in Wilson's disease." (PMID 25870938, 2016). "Interestingly, patients with Wilson’s disease caused by ATP7B mutation usually also show Parkinson’s like symptoms, such as cogwheel rigidity, bradykinesia or slowed movements and a lack of balance." (PMID 27380887, 2016). "ATP7B is a known gene associated with Wilson disease, which is a disorder characterized by the deposition of copper in the liver, brain, and other tissues, leading to neurological and cognitive deterioration including memory loss, tremors, and emotional changes." (PMID 27535846, 2016). "While Wilson's disease is an autosomal recessive disorder caused by mutations in the ATP7B gene, it has been hypothesized that a single mutated ATP7B allele may act as a risk factor for (late-onset) parkinsonism." (PMID 24672633, 2014). "Wilson disease (WD) is an autosomal recessive disorder characterized by mutations in the ATP7B gene which is responsible for copper (Cu) metabolism and excretion, with Cu accumulation in liver, and brain, that leads to progressive liver damage, as well as neurological and psychiatric manifestations." (PMID 24810691, 2014). "Mutations in the copper transporter ATP7B cause copper overload and toxicity in Wilson disease." (PMID 24909901, 2014). "Menkes disease is caused by a mutation in the gene encoding the copper transporter ATP7A that results in severe copper deficiency in the brain, and Wilson's disease is caused by a mutation in the gene encoding the copper transporter ATP7B, resulting in copper accumulation in the brain." (PMID 24672633, 2014). "Furthermore, iron overload was reported in Wilson disease, a genetic disorder caused by the mutation in ATP7B gene." (PMID 25247420, 2014).
Wilson disease (continued). "The Multiplex ARMS assay was then subsequently tested in 65 patients with Wilson disease with known and unknown ATP7B mutations." (PMID 24003324, 2013). "Wilson disease is a rare disorder of copper metabolism due to mutation in ATP7B gene." (PMID 24003324, 2013). "In ATP7B, the mutation of D1027 (the residue analogue to D1044) prevents the formation of the acyl-phosphate intermediate, and is associated with a complete loss of the copper-transport activity of ATP7B in Wilson’s disease." (PMID 22992316, 2012). "We examined the ATP7B mutation spectrum in Wilson disease patients in Iran." (PMID 22308153, 2011). "Patient P4, with the rare inherited disorder Wilson's disease, presented two known heterozygous ATP7B mutations (c.2333G>T, p.R778L; c.2810detT, MIM# 606882); 127 of the 254 reads at this locus carried the prevalent substitution mutation, and almost half of the reads included the deletion mutation." (PMID 22216297, 2011). "Wilson disease (WD) is a rare autosomal recessive disorder of copper metabolism caused by damaging changes in both copies of the ATP7B gene, which encodes a copper-transporting P-type ATPase." (PMID 41270864, 2025). "Wilson disease (WD) is a genetic disorder of copper metabolism caused by ATP7B mutations, leading to hepatic and systemic copper accumulation." (PMID 41480142, 2025). "Wilson disease (WD) is an autosomal recessive disorder caused by mutations in ATP7B, which encodes a copper-transporting P-type ATPase that promotes copper excretion from bile." (PMID 40629618, 2025). "Wilson disease (WD) is an inherited disorder caused by ATP7B mutations, resulting in toxic copper accumulation primarily in the liver and brain." (PMID 41230834, 2025). "Wilson disease (WD) is an inherited, autosomal recessive disorder due to an ATP7 B gene mutation, resulting in defective copper metabolism and leading to progressive hepatolenticular damage." (PMID 40688890, 2025). "Furthermore, while the patients with Wilson disease included in our study have been clinically diagnosed, the effects of various ATP7B mutations, such as P992L, A874P, R778L, and c.1543 + 1G>T, may differ." (PMID 40384935, 2025). "Case P4, an individual of Egyptian origin, is homozygous for a missense variant in the ATP7B gene, which encodes a copper-transporting ATPase associated with Wilson disease (WD; MIM #277900)." (PMID 41040850, 2025). "Wilson disease (WD) is an autosomal recessive disorder in which mutations in ATP7B lead to excessive copper deposition in the liver, brain, eyes, kidneys, and other organs." (PMID 40629618, 2025). "BACKGROUND: Wilson disease (WD) is an autosomal recessive disorder caused by variants in the ATP7B gene, leading to copper metabolism dysfunction and multi-organ damage." (PMID 41454338, 2025). "Wilson disease (WD) is a rare, autosomal recessive disorder due to excessive copper accumulation mainly in the liver and the brain due to mutations in ATP7B gene." (PMID 41029868, 2025). "Wilson Disease (WD) is an autosomal recessive disorder caused by mutations in the ATP7B gene on chromosome 13, resulting in defective copper transport." (PMID 41223192, 2025). "Wilson disease (WD) is a rare autosomal recessive disorder of copper metabolism, caused by biallelic mutations in homo- or compound heterozygous states in the ATP7B gene." (PMID 39261850, 2024). "Genetic screening for pathogenic ATP7B variants could help with the diagnosis of Wilson’s disease." (PMID 39020067, 2024). "Inactivating mutations in ATP7A and ATP7B lead to Menkes disease and Wilson disease (WD), respectively." (PMID 38715962, 2024). "Variants in ATP7B resulted in a rare autosomal recessive disorder of copper metabolism, Wilson disease (WD), also called progressive lenticular degeneration." (PMID 39767564, 2024).
Wilson disease (continued). "However, an excess of copper is harmful to the human body, and the accumulation of copper causes liver tissue damage in Wilson’s disease (WD), a potentially lethal genetic disorder caused by a mutation in the ATP7B gene, which encodes a copper efflux transporter." (PMID 39274933, 2024). "Wilson disease (WD) is a hereditary disorder of copper metabolism resulting from various mutations in the ATP7B gene." (PMID 39512437, 2024). "Wilson disease (WD) is an autosomal recessive disorder resulting from ATP7B gene dysfunction due to mutation, leading to copper accumulation in various tissues, primarily in the liver and brain." (PMID 39020387, 2024). "Thus, further studies on rare variants in the ATP7B gene will be needed to guide laboratories whether those variants need to be reported and to improve the diagnostic yield of Wilson’s disease." (PMID 39020067, 2024). "Hepatolenticular degeneration (HLD), commonly referred to as Wilson disease (WD), is an infrequent autosomal recessive neurological disorder resulting from mutations occurring in the ATP7B gene." (PMID 37759104, 2024). "Wilson disease (WD) is an inherited disorder of copper metabolism caused by mutations in ATP7B (hepatomegaly protein)." (PMID 37539053, 2023). "Wilson disease (WD) is a life-threatening autosomal disorder of copper homeostasis caused by pathogenic variants in copper transporter ATP7B and characterized by toxic copper accumulation, resulting in severe liver and brain diseases." (PMID 37707949, 2023). "Dysregulation of copper metabolism is disadvantageous for cells because mutations in ATP7A and ATP7B are directly responsible for Menkes disease (MD) and Wilson disease (WD), respectively." (PMID 37767404, 2023). "Wilson Disease (WD) is a recessive genetic disorder caused by pathogenic variants of ATP7B that leads to copper accumulation, resulting in hepatic, neurologic, and psychiatric problems when left untreated." (PMID 37333007, 2023). "Wilson disease (WD) is an autosomal recessive disorder of copper metabolism due to mutations in the ATP7B gene that encodes copper-transporting P-type ATPase." (PMID 37717021, 2023). "Accordingly, we aimed to study whether copper excess affects intracellular selenium levels, and SELENOP distribution and excretion of cultured hepatocytes and whether the findings are compatible with data from genetic models of ATP7B mutations in rats and Wilson’s disease patients." (PMID 37311819, 2023). "Wilson disease (WD) is a disorder of copper metabolism mediated by autosomal recessive inherited mutations of the ATP7B gene on chromosome 13q." (PMID 37226184, 2023). "Wilson disease (WD) is an autosomal-recessive disorder of copper (Cu) metabolism caused by inborn mutations in the Cu(I) transporting ATPase beta polypeptide (ATP7B)." (PMID 35586338, 2022). "Mutations in ATP7B leads to Wilson disease (WD), which is characterized by an inability to excrete Cu into the bile and therefore hepatic Cu accumulation." (PMID 34207741, 2021). "Wilson disease (WD) is caused by inactivation of the copper transporter Atp7b and copper overload in tissues." (PMID 33707579, 2021). "Wilson disease (WD) is a systemic disease caused by the inheritance of recessive mutations affecting the ATP7B copper transporter gene." (PMID 34098115, 2021). "The pathogenesis of Wilson disease (WD) involves hepatic and brain copper accumulation resulting from pathogenic variants affecting the ATP7B gene and downstream epigenetic and metabolic mechanisms." (PMID 34098115, 2021). "Genetic alteration in Cu-regulating ATPases, ATP7A, and ATP7B can cause Menkes disease (MD) and Wilson disease (WD), respectively." (PMID 34577062, 2021). "Wilson disease (WD) is an Autosomal-Recessive disorder due to mutations of ATP7B gene on chromosome 13q14.3." (PMID 32532207, 2020).